CAT (catalase)
Diseases named in the same sentence as CAT in open-access papers (continued):
Sharing a sentence is not in itself a finding about the gene and the disease.
hyperlipidemia (28 papers, 2013 to 2025). "PSP is beneficial in HFD-induced obese rats, as it improves hyperlipidemia, decreases BW, hepatic malondialdehyde, and inflammatory cytokine levels, and increases the hepatic catalase and superoxide dismutase activities." (PMID 40278571, 2025). "Psyllium husk ethanolic extract can reduce lipid peroxidation, increase CAT and GSH activities, and increase the hormones, leptin, and adiponectin associated with hyperlipidemia." (PMID 33923513, 2021). "Carriers of at least one polymorphic CAT rs1001179 allele were significantly more likely to be NYHA class 2 (OR = 4.09, 95% CI = 1.37-12.25, P = 0.012), even after adjustment for hyperlipidemia and BMI (OR = 4.14, 95% CI = 1.22-14.09, P = 0.023)." (PMID 33425072, 2020). "In the present study, HFD-induced hyperlipidemia was associated with significant increase in hepatic lipid peroxidation and diminished GSH, SOD, CAT, and GPx." (PMID 31527433, 2019). "The model group exhibited lower levels of catalase (CAT), glutathione peroxidase (GSH-PX), superoxide dismutase (SOD), and peroxidase (POD) compared to the control group, indicating a compromised antioxidative capacity in the liver caused by hyperlipidemia." (PMID 37755081, 2023). "Moreover, PFAc was found to enhance the total antioxidant capacity as well as GSH, SOD and CAT activities, which were reduced by Triton WR-1339-induced hyperlipidemia." (PMID 37297342, 2023). "The levels of GSH, SOD and CAT were significantly decreased (P-values less than 0.0001, 0.001 and 0.01, respectively), indicating that the cellular antioxidant capacity was impaired and accelerated the hyperlipidemia process." (PMID 35990322, 2022). "The present study showed a significant serum MDA flow and diminution in serum GSH and CAT in hyperlipidemic rats versus the CON group, which may be due to metabolic disorders caused by hyperlipidemia." (PMID 33923513, 2021). "Carriers of at least one polymorphic CAT rs1001179 A allele were significantly more likely to exhibit mild symptoms of heart failure according to NYHA classification in our study, even after taking into account hyperlipidemia and BMI." (PMID 33425072, 2020). "DPx treatment significantly decreased TAA-induced hyperlipidemia as evidenced by the decreased AST, ALT, ALP, γ-GTP and serum TG concentrations and reduced the activities of catalase (CAT) and superoxide dismutase (SOD) activity." (PMID 37324954, 2023). "Conversely, hyperlipidemia results in the depletion of protective antioxidants, such as glutathione (GSH), and inhibits free radical scavenging enzymes, including catalase (CAT), superoxide dismutase (SOD), and glutathione peroxidase (GPx)." (PMID 33473299, 2021). "As, DCC augments the antioxidant system by enhancing the activities of antioxidant enzymes SOD, CAT, GPx and TAS, on one hand and decreasing hyperlipidemia, on the other hand." (PMID 29121952, 2017). "In the in vitro experiments, we have found that PCE can effectively reduce OA-induced adipogenesis in HepG2 cells, reduce the levels of TG and MDA in the hyperlipidemia cell model, increase GSH content and GSH-px, CAT, and SOD enzyme activity, and improve the level of cellular OS." (PMID 34925692, 2021). "In results, cyanate induced hyperlipidemia and oxidative stress by influencing the content of total cholesterol (TC), high-density lipoprotein (HDL), low-density lipoprotein (LDL), superoxide dismutase (SOD), catalase (CAT) in liver." (PMID 31491954, 2019). "In our study, the reduced effect of glycine on GPX1 and the increased activities of CAT and Cu/Zn-SOD may be related to enhanced insulin signaling and sensitivity and reduced fat accumulation and hyperlipidemia." (PMID 29675131, 2018). "In addition to hyperlipidemia, the Ch Group animals showed enhanced oxidative stress, as evidenced by increased MDA levels and decreased CAT activity and GSH levels." (PMID 24119413, 2013).
hyperlipidemia (continued). "Hyperlipidemia may down-regulate the antioxidant capacity in tissues and cells, thereby increasing the levels of superoxide free radicals, H2O2, and MDA and further reducing the activities of T-AOC, SOD, CAT, and GSH-Px in tissues or serum." (PMID 36615439, 2022). "In this study, the SOD, CAT content in the cyanate group decreased significantly compared with the control group, and the content of MDA and NO increased significantly, which indicated an impaired antioxidant capacity and acceleration of the hyperlipidemia process." (PMID 31491954, 2019). "Moreover, HLF could significantly reduce the levels of NLRP3, caspase-1, IL-1β, IL-6, IL-18, and TNF-α and increase the activities of plasma SOD, CAT, and GSH-PX, which suggested that HLF could effectively relieve the inflammatory response and oxidative stress induced by hyperlipidemia." (PMID 36425260, 2022). "Therefore, to verify whether PCE has antioxidant properties that prevent OA-induced HepG2 cells from hyperlipidemia, the effects of PCE on MDA and GSH production and ROS scavenging enzyme (GSH-Px, CAT, and SOD) activities in OA-induced HepG2 cell influences were investigated." (PMID 34925692, 2021).
steatosis (27 papers, 2008 to 2026). Increased lipid within the cytoplasm of cells. "The diminished expression and activity of ROS detoxification mechanisms (e.g., SOD, catalase or GSH) with steatosis have also been reported in mammalian in vitro and in vivo experiments." (PMID 39056688, 2024). "To further elucidate the role of CAT in 13-HODE-induced hepatocyte steatosis, we used a Cat-expressing plasmid to overexpress Cat in hepatocytes." (PMID 38071367, 2023). "Because oxidative stress is initiated during an early stage of steatosis, consistently high CAT activity is observed." (PMID 37759451, 2023). "This was accompanied by increased superoxide dismutase, glutathione peroxidase and catalase and decreased nitric oxide synthase in the liver of resveratrol group significantly (P < 0.05 vs steatosis group)." (PMID 18782455, 2008). "Although the results of research on catalase activity in steatosis in humans are often conflicting, the overproduction of ROS and disease progression are undoubtedly conducive to the inactivation of antioxidant enzymes, disturbing the oxidant/antioxidant balance." (PMID 38397849, 2024). "CAT overexpression attenuated 13-HODE-induced hepatocyte steatosis." (PMID 38071367, 2023). "Meanwhile, the content of CAT and the mRNA expression level of Sod2 in the steatosis LO2 cells decreased compared with the normal control and the taurine prevention groups, indicating an antioxidant capacity of taurine on both the FLHS hens and the steatosis LO2 cells." (PMID 37373507, 2023). "Moreover, by overexpressing or knocking down Cat in hepatocytes, we found that CAT mediates 13-HODE-induced steatosis." (PMID 38071367, 2023). "Similar results were obtained in a study in mice, in which steatosis associated with the development of non-alcoholic steatohepatitis (NASH) and non-alcoholic fatty liver disease (NAFLD) was accompanied by a reduction in the activity of antioxidant enzymes, including catalase, in hepatocytes." (PMID 38397849, 2024). "Cashew nut oil, a new plant‐based product, has been shown to reduce blood glucose, triglycerides, uric acid, hepatic foci of microvesicular steatosis, and increase SOD expression and activity and catalase activity." (PMID 41103188, 2026). "Expression of hepatic genes related to lipid metabolism (Cpt1a, Atgl, Mgl, Dgat2, Srebp, Plin2) and OS (catalase, Edem) were modulated by FB23, although hepatic steatosis remained unchanged." (PMID 39984825, 2025). "In HepG2 cells with steatosis, PGAM5 knockdown reduced insulin sensitivity, increased mTOR phosphorylation and reduced the expression of NRF2, catalase (CAT), HO-1 and GPX6." (PMID 37605246, 2023). "We observed a significant enhancement in AST, ALP, LDH, TG, and MDA levels and diminution in GSH amount, and SOD, CAT and GPX activity as well as microvesicular steatosis and periportal inflammation in BPA-treated rats." (PMID 34290970, 2021). "Myricetin significantly reduced HFD‐induced steatosis, TBARS levels, and lipid accumulation along with showed enhancement in SOD, glutathione peroxidase (GPx) and catalase (CAT) antioxidant enzyme activities in the liver." (PMID 34646551, 2021). "GAtreatment was shown to boost the activity of including catalase, essentialantioxidant enzymes, glutathione peroxidase and superoxide dismutase,while also reducing lipid accumulation in the kidneys, indicatinga protective effect against HFD-induced steatosis." (PMID 39365293, 2024). "In addition, HLF increased the activities of plasma SOD, CAT, and GSH-Px and decreased the levels of Casp 1, NLRP3, IL-1β, IL-18, and TNF-α, improving the degree of hepatocyte steatosis and inflammatory infiltration of rats." (PMID 36425260, 2022).
epilepsy (26 papers, 2012 to 2025). A brain disorder characterized by episodes of abnormally increased neuronal discharge resulting in transient episodes of sensory or motor neurological dysfunction, or psychic dysfunction. "Oxidative stress is responsible for neuronal loss and death, which are directly related to epilepsy in in vitro animal models, and disturbs the antioxidant systems, including catalase (CAT), glutathione (GSH), superoxide dismutase (SOD), and lipid peroxidation (malondialdehyde [MDA]) systems." (PMID 37695764, 2023). "Catalase administration decreased the contractile responses only in the rings of rats with epilepsy." (PMID 37099815, 2023). "With respect to the etiology of epilepsy, significant decreases of 1.1-fold in CAT activity (p < 0.0001) and of 1.2-fold in 3-NT levels (p < 0.0001) in symptomatic epilepsy were observed in comparison with those in idiopathic epilepsy." (PMID 30622673, 2018). "On the other hand, there are also studies, with very weak (unchanged SOD, CAT, GPX and GR activities) or even opposite (decreased lipid peroxidation markers) association of oxidative stress with epilepsy." (PMID 23730257, 2012). "In another study, CAT activity has been found to be lower in epilepsy patients." (PMID 38509121, 2024). "SOD and CAT appear to be the main antioxidant enzymes responsible for maintaining the balance between the production of reactive species and the endogenous defense system in epilepsy." (PMID 39202580, 2024). "Biochemical analyses revealed that epilepsy induction significantly elevated MDA levels while reducing SOD activity and CAT content in hippocampal tissues, indicating pronounced oxidative stress." (PMID 40880740, 2025). "In conclusion, our study shows that significantly increased levels of SOD and CAT and significantly decreased levels of GR and GPx, as well as GSH concentrations, were observed in patients with epilepsy compared to control subjects." (PMID 39202580, 2024). "Aiming to observe the antioxidant ability of hippocampal tissue after epilepsy, we firstly measured the activities of SOD, CAT, and GSH-Px." (PMID 37876811, 2023). "MO ameliorated oxidative stress by increasing GSH levels, SOD and CAT activities; and decreasing MDA levels in the PTZ-kindled rats, thus corroborating the therapeutic benefits of MO in the management of epilepsy." (PMID 34721045, 2021). "As already discussed, most of the studies that investigate OS in epilepsy focus on serum lipid peroxide (especially MDA) and erythrocyte antioxidative enzyme activity (especially SOD, GPx, and CAT)." (PMID 33066477, 2020). "Decreased activity of CAT and SOD1 in the plasma suggests a reduced antioxidant defense capacity in epilepsy patients." (PMID 33082886, 2020). "Increased activities of SOD and CAT, and decreased activities of GPX and glutathione reductase (GR) was observed in numerous studies in drug-naive patients with epilepsy." (PMID 23730257, 2012). "To study the effects of LEV on antioxidant–oxidant activity in long-term epilepsy, we determined the SOD, CAT, GPx and GR activities; GSH levels; and H2O2, carbonylated protein, MDA and 8-OHdG oxidant stress marker levels in the hippocampi of TLE model animals at 5.7 months (23 weeks) after SE." (PMID 39273262, 2024). "In the early stage of epilepsy (14 weeks post-SE), LEV administration significantly increased the activity of SOD and CAT in the hippocampi of epileptic rats compared with that in the hippocampi of untreated epileptic controls, and similar observations have been reported in other studies." (PMID 39273262, 2024). "In general, low SOD and CAT and high MDA levels were found in epilepsy patients in the literature." (PMID 38509121, 2024). "With respect to the oxidant–antioxidant effects of LEV during the progression of epilepsy, LEV was able to maintain lipid peroxidation, nitrite–nitrate and GSH levels and CAT activity at normal values in the hippocampi of animals pretreated with LEV (i.e., before SE)." (PMID 39273262, 2024).
epilepsy (continued). "The effect of ROS-stimulated epilepsy was apparent in this study, as indicated by increased levels of oxidative markers (LPO, NO, GSH, and 8OHdG) and reduced levels of antioxidant markers (SOD, CAT, GR, and GPx) after PTZ injection." (PMID 37509594, 2023). "Besides, piperine increased the antioxidant parameters through reduction of the glutathione level, inhibition of catalase and COX-2, thus exerting neuroprotection against pilocarpine-induced epilepsy in rats." (PMID 34943096, 2021). "In addition, research showed that catalase activity, glutamate, and GSH were significantly increased following epilepsy, and ROS generation rise in CA1, CA3, and dentate gyrus with a marked caspase-3 expression." (PMID 33921725, 2021). "Oxidative stress in patients with epilepsy treated with AEDs was assessed by measuring serum, plasma, erythrocyte, leukocyte or urine markers of macromolecular damage (MDA, RCD, P-SH, 8-OHdG, 15F-2t-isoP) and antioxidative enzyme activity (SOD, GPX, CAT, GR)." (PMID 23730257, 2012). "Likewise, valproic acid, a histone deacetylase inhibitor used for treatment of epilepsy and other conditions, has been shown to increase levels of SOD, glutathione peroxidase, and catalase in rat retinas exposed to ischemia/perfusion injury, while correspondingly decreasing cell death." (PMID 30373222, 2018). "Although this ratio has not been studied in epilepsy, a study in the brains of aging mice revealed a correlation between an altered SOD/GPx + CAT ratio and increased lipid damage." (PMID 39273262, 2024). "Additionally, the second aim of this study is to determine the levels of superoxide dismutase (SOD), catalase (CAT), reduced glutathione (GSH) and malondialdehyde (MDA) in resistant epilepsy patients who have not been studied before." (PMID 38509121, 2024).
glioblastoma (26 papers, 2012 to 2026). The most malignant astrocytic tumor (WHO grade IV). "Higher activities and expression of glutathione-S-transferase (GST) and CAT were recorded in radioresistant variant of human glioblastoma cell line after in vitro fractionated γ-irradiation with 3 Gy." (PMID 22645500, 2012). "We found that the 3 glioblastoma cell lines are extremely susceptible to ascorbic acid revealed reduced activity of intracellular catalase." (PMID 22551313, 2012). "This coordinated activation of MnSOD, catalase, and GPx enables glioblastoma cells to tolerate high ROS microenvironments, facilitating survival in metabolically stressed or inflamed tumor niches." (PMID 40452834, 2025). "The role of CAT in glioblastoma presents a complex and seemingly paradoxical picture that requires careful interpretation of the existing literature." (PMID 41009025, 2025). "An increase in the mRNA expression of SOD2, GSR, and GPX4 was observed only in the MDR glioblastoma cell line, while CAT mRNA expression levels remained unchanged upon treatment with 2 and 5 in both cell lines." (PMID 41471777, 2025). "For instance, it mediated glioblastoma survival through catalase-mediated hydrogen peroxide clearance." (PMID 38627816, 2024). "We found that 1166 μM nitrite did not exhibit any cytotoxicity, while 750 μM hydrogen peroxide as well as PAL with catalase (hydrogen peroxide concentration of < 50 nM) completely killed the glioblastoma cells." (PMID 34531507, 2021). "In the glioblastoma model, the catalase activity of the frontal cortex and hippocampus was significantly decreased in the rats of C6 control group as compared to the normal control group." (PMID 32995109, 2020). "Adding exogenous catalase to glioblastoma cell lines protected them against the toxic effect of ascorbic acid." (PMID 22551313, 2012). "Moreover, CLO inhibits growth and inhibits genes related to OS defense (thioredoxin peroxidase, glutaredoxin, nitric oxide oxidoreductase, cytochrome c peroxidase and b5 reductase, GPx, SOD1, SOD2, and CAT) in glioblastoma patient biopsy-derived cell cultures." (PMID 41154163, 2025). "Hence, this study aimed to explore the possible effect of the SP/NK1R system and aprepitant, a potent NK1R antagonist, on the expression and activity of catalase and superoxide dismutase enzymes, two of the most well-known antioxidant enzymes, in U87 glioblastoma cancer cells." (PMID 33976938, 2021). "The authors concluded that aprepitant inhibits SP’s oxidizing effects by inducing the antioxidant effects of catalase and SOD in the U87 cell line, suggesting it as a potential candidate for controlling glioblastoma in animal models and clinical trials." (PMID 41009025, 2025). "A novel biodegradable nanocomplex (CSI) was developed by catalase (CAT) encapsulation into SiO2 nanoparticles (CAT@SiO2) and ICG as a sonosensitizer for glioblastoma treatment." (PMID 39206442, 2024). "This study aimed to evaluate the effects of the SP/NK1R system on the expression and activity of catalase and superoxide dismutase (SOD) in the glioblastoma U87 cancer cell line." (PMID 33976938, 2021). "To eliminate the cytotoxic effect of hydrogen peroxide in PAL, we treated PAL with catalase (0.5 mg/ml in PAL) for 2 h before glioblastoma cells were treated with the PAL, and the hydrogen peroxide concentration was less than 50 nM after catalase treatment." (PMID 34531507, 2021). "We demonstrated that TP4 not only induces ROS production but also diminishes antioxidant defenses through the suppression of catalase and GPX, possibly rendering TP4 more cytotoxic in glioblastoma cell lines." (PMID 30717309, 2019). "Previous studies have shown that catalase and superoxide dismutase were greatly increased in TMZ-resistant glioblastoma cells." (PMID 30717309, 2019).
glioblastoma (continued). "Recent studies have shown that resveratrol induces the elevation of intracellular ROS by attenuating SOD2 and CAT expression and promoting the activity of caspase-9 and caspase-3, thereby remarkably arresting proliferation and triggering extensive apoptosis in glioblastoma multiforme (GBM) cells." (PMID 36558995, 2022). "Glioblastoma cells adapt to the oxidative stress induced by chemotherapy by upregulating antioxidant systems such as glutathione (GSH) and thioredoxin (Trx), as well as enzymes such as superoxide dismutase (SOD) and catalase (CAT), thus promoting survival and contributing to therapy resistance." (PMID 41471777, 2025). "The glioblastoma cell line U-251, extremely sensitive to the exposure to ascorbic acid (EC50: 2.6 mmol/L), was incubated with 10 mmol/L ascorbic acid, the toxic concentration for this cell line, and different concentrations of catalase (250 - 1000 U/mL) for 4 h." (PMID 22551313, 2012). "Anti-oxidant genes such as CAT, SOD2, and GPX1 were not elevated in PAM- or PAL-treated glioblastoma cells." (PMID 31541175, 2019).